RNU1-43P (RNA, U1 small nuclear 43, pseudogene)
Gene: Small nuclear RNA gene on chromosome 3 (103,159,960 to 103,160,124, forward strand). Ensembl gene ENSG00000201922.
Homologues: Orthologues: chimpanzee U1 (99% identical), macaque U1 (93% identical), rabbit U1 (65% identical). Paralogues in human: RNU1-67P (84% identical), RNU1-1 (84% identical), RNU1-2 (84% identical), RNU1-27P (84% identical), RNU1-28P (84% identical), RNU1-3 (84% identical), RNU1-4 (84% identical), RNVU1-18 (84% identical), RNVU1-29 (84% identical), U1 (84% identical), RNVU1-28 (83% identical), RNVU1-7 (83% identical), and 133 more.